CX3CL1 (C-X3-C motif chemokine ligand 1)
Diseases named in the same sentence as CX3CL1 in open-access papers (continued):
Sharing a sentence is not in itself a finding about the gene and the disease.
atopic dermatitis (2 papers, 2025). "Gene expression of the chemokine receptor CX3CR1 was also found to decrease; CX3CR1 and its ligand CX3CL1 have been reported to contribute to atopic dermatitis." (PMID 40077628, 2025).
benign ovarian tumors (2 papers, 2011 to 2022). "Messenger RNA for CX3CL1 was visualized by RT-PCR, which generated a product of the expected size (387 bp) from three healthy ovary samples, in six specimens from benign ovarian tumors, three borderline specimens and nine EOC specimens." (PMID 21750716, 2011).
Chagas disease (2 papers, 2018 to 2025). A parasitic infection caused by Trypanosoma cruzi. "Altogether, there remains a promising avenue of investigation into the inhibition of the CX3CR1/CX3CL1 axis in the context of Chagas disease." (PMID 40936920, 2025).
clear cell renal cell carcinoma (2 papers, 2022). "Among these data, those for KIRC (KIRC is another name for clear cell renal cell carcinoma) piqued our interest; however, the function of CX3CL1 in clear cell renal cell carcinoma (ccRCC) remained unclear." (PMID 36397015, 2022). "However, the function of CX3CL1 in clear cell renal cell carcinoma (ccRCC) remains poorly defined." (PMID 36397015, 2022). "For example, although a four-gene signature (composed of NCR1, PRF1, CX3CL1 and CX3CR1) was shown to accurately distinguish NK-high vs NK-low subgroups in clear cell renal cell carcinoma, these genes are ubiquitously expressed by many immune cell types." (PMID 36685584, 2022).
crescentic glomerulonephritis (2 papers, 2019 to 2024). A histopathologic term for a pattern of diseases characterized by extensive crescent formation in the glomeruli; patients present clinically with rapid deterioration of renal function, and possible progression to end-stage renal failure within weeks or months. "CX3CL1 mRNA expression has been observed in glomerular lesions of patients with vascular disease, and in a rat model of crescentic glomerulonephritis, inhibition of CX3CR1 attenuated glomerular leukocyte influx and reduced crescent formation." (PMID 38937701, 2024).
deep vein thrombosis (2 papers, 2025). "Inhibition of CX3CL1/CX3CR1 in a mouse model of deep vein thrombosis delays thrombolysis and may have the side effect of exacerbating DVT." (PMID 40508161, 2025).
delirium (2 papers, 2018 to 2025). A disorder characterized by confusion; inattentiveness; disorientation; illusions; hallucinations; agitation; and in some instances autonomic nervous system overactivity. "The utility of astrocytic and microglial plasma biomarkers, including chitinase-3-like protein 1, translocator protein (18 kDa), CX3CL1 and CSF1, which are currently being trialled for other disorders should also be explored in the context of delirium." (PMID 39463449, 2025).
demyelination (2 papers, 2023 to 2025). "In an acute demyelination mouse model, activated astrocytes express multiple ligands, including Cx3cl1, Csf1, Il34, and Gas6, which act on both homeostatic and activated microglia, thereby potentially mediating microglial activation, recruitment, and enhancing their phagocytic activity." (PMID 40292254, 2025).
dengue (2 papers, 2015 to 2017). "In wild-type mice, mast cells responding to dengue virus infection upregulated chemokine expression (RANTES/CCL5, SDF-1/CXCL12, and fractalkine/CX3CL1), and mediated recruitment of NKT cells (CD3+NK1.1+) into the skin at sites of dengue virus infection." (PMID 26074921, 2015).
dermatitis (2 papers, 2018 to 2025). An inflammatory process affecting the skin. "Additionally, patients who developed dermatitis showed decreased levels of plasma CX3CL1, vascular endothelial growth factor-alpha (VEGF-α), and MHCI-related peptides 1–3 months after ICI treatment." (PMID 40894206, 2025).
dyslipidaemia (2 papers, 2022 to 2025). "In conclusion, we evaluated the activation of the CX3CL1/CX3CR1 axis in subjects with FCH, a human genetic model of mixed dyslipidaemia and IR." (PMID 41153665, 2025).
fibromyalgia (2 papers, 2017 to 2022). A chronic disorder of unknown etiology characterized by pain, stiffness, and tenderness in the muscles of neck, shoulders, back, hips, arms, and legs. "The top five proteins that distinguished fibromyalgia patients from plasma controls were in serum STAMBP, SIRT2, CD40, AXIN1 and IL-7 and in CSF (CCL19, CCL23, IL-18, CX3CL1, FGF19, CXCL10, CCL11)." (PMID 36327322, 2022).
Gliosis (2 papers, 2022 to 2025). Gliosis is the focal proliferation of glial cells in the central nervous system. "Gliosis and CX3CL1/CX3CR1 expression were also analyzed in the anterior cingulate cortex (ACC) and periaqueductal gray matter (PAG) since they are supraspinal structures involved in pain perception and modulation." (PMID 36056079, 2022).
Glucose intolerance (2 papers, 2020 to 2023). Glucose intolerance (GI) can be defined as dysglycemia that comprises both prediabetes and diabetes. "CX3CL1 is rapidly induced after the introduction of an HFD, and its inhibition impaired the induction of obese and glucose intolerance phenotypes." (PMID 33029514, 2020).
Headache (2 papers, 2024). Cephalgia, or pain sensed in various parts of the head, not confined to the area of distribution of any nerve. "In accordance with our data, recent findings have demonstrated significantly increased concentrations of CX3CL1 in cerebrospinal fluid (CSF) both during headache episodes and interictally, compared to control groups." (PMID 38890625, 2024). "Serum levels of CX3CL1 were increased in the worsened (2145 [811–4866] pg/ml) and new onset (1668 [0-7357] pg/ml) headache group as compared to patients with no (1129 [0-5379] pg/ml) or unchanged (1478 [346–4332] pg/ml) headaches." (PMID 38890625, 2024). "We found that CX3CL1, the ligand to the fractalkine receptor, is increased in humans irrespective of the headache status." (PMID 38561692, 2024).
HIV-1 infection (2 papers, 2013 to 2024). The type species of lentivirus and the etiologic agent of acquired immunodeficiency syndrome (AIDS). "CX3CL1 and its receptor CX3CR1 have received increased attention regarding their roles in HIV-1 infection and in HAND specifically." (PMID 24147028, 2013).
Huntington disease (2 papers, 2023). Huntington disease (HD) is a rare neurodegenerative disorder of the central nervous system characterized by unwanted choreatic movements, behavioral and psychiatric disturbances and dementia. "In contrast, in Huntington’s disease, there was a low expression in protein and gene coding CX3CL1." (PMID 37175729, 2023).
Hyperinsulinemia (2 papers, 2021 to 2022). An increased concentration of insulin in the blood. "Additionally, studies have shown that high CX3CL1 levels can lead to depletion of functional reserves of β cells and chronic hyperinsulinemia, while inhibition of CX3CL1/CX3CR1 system can regulate pancreatic islet β-cell function." (PMID 34054797, 2021). "More evidence supports that initial increase of insulin secretion by CX3CL1/CX3CR1 may be just a defensive reaction to inflammation, which can lead to chronic hyperinsulinemia and depletion of functional reserves of β-cells." (PMID 35370759, 2022).
IgA nephropathy (2 papers, 2021 to 2025). "A previous study investigated serum CX3CL1 levels and renal prognosis in Chinese patients with IgA nephropathy." (PMID 40508161, 2025). "In another report, stimulation of peripheral blood mononuclear cells from patients with IgA nephropathy with lipopolysaccharides increased the protein and gene expression of CX3CR1 compared to healthy controls, and cells from patients with active disease were more sensitive to CX3CL1." (PMID 40508161, 2025).
Impaired glucose tolerance (2 papers, 2024 to 2025). An abnormal resistance to glucose, i.e., a reduction in the ability to maintain glucose levels in the blood stream within normal limits following oral or intravenous administration of glucose. "It has been demonstrated that CX3CL1 concentrations manifest a notable elevation in the serum of individuals with impaired glucose tolerance, exhibiting a marked correlation with fasting blood glucose levels." (PMID 38606083, 2024).
infarction (2 papers, 2020 to 2024). A localised pathological necrosis of tissue resulting from obstruction of the blood supply usually by a thrombus, an embolus, or vascular torsion. "Additionally, in vivo studies in mouse models of AMI found an increase in the expression of CX3CL1 during phase 2 of infarction, which suggested the mobilization of Ly-6Clow monocytes (mouse counterparts of human CD14++CD16+/CD14+CD16++ monocytes)." (PMID 32676508, 2020). "Similar studies in CX3CL1−/− and CX3CR1−/− mice have shown that in both strains of mice, the volume of infarcted tissue after ischemia is lower, and the administration of exogenous CX3CL1 to WT mice reduces the total volume of tissue affected by ischemic infarction." (PMID 39062768, 2024).
leukoplakia (2 papers, 2016 to 2022). A white patch or plaque on a mucous membrane that cannot be characterized clinically or pathologically as any other disease. "In addition, leukoplakia also secretes low a CX3CL1, a potential antifungal protein, which is more resistance to Candida albicans." (PMID 36548207, 2022).
liver cirrhosis (2 papers, 2021 to 2024). "CX3CL1 is known to be upregulated in chronic liver disease and HCC; surprisingly, high CX3CL1 levels in liver cirrhosis and HCC correlated with better patient prognosis." (PMID 39684877, 2024).
lymphoma (2 papers, 2018 to 2023). A malignant (clonal) proliferation of B- lymphocytes or T- lymphocytes which involves the lymph nodes, bone marrow and/or extranodal sites. "Nevertheless, the “find-me” signal CX3CL1/fractalkine was found to be released from apoptotic B lymphocytes in association with ApoMVs and the chemoattractive molecule ICAM-3 was associated with ApoEVs generated from apoptotic lymphoma cells." (PMID 30002658, 2018).
metastatic disease (2 papers, 2021 to 2024). "The influences of CX3CL1 on nonmetastatic and metastatic tumors." (PMID 38775151, 2024).
myocardial ischemia (2 papers, 2021 to 2025). A disorder of cardiac function caused by insufficient blood flow to the muscle tissue of the heart. "Knockdown of CX3CL1 reverse the protective effect of ad-NPAS2 on rat myocardial ischemia-reperfusion injury and H/R-induced cardiomyocyte apoptosis." (PMID 34460437, 2021).
Nephroblastoma (2 papers, 2022 to 2023). An embryonal neoplasm characterized by the presence of epithelial, mesenchymal, and blastema components. "It was found that the methylation of chemokine DNA was significantly different in tumours and para-tumour tissue, and the CX3CL1 gene was seriously hypermethylated at cg27664018 in Wilms tumour tissues." (PMID 35530333, 2022). "In addition, the serum levels of IFN-α-induced chemokines used to monitor SLE and CX3CL1 methylation predicted T-cell infiltration in nephroblastoma." (PMID 37198402, 2023). "Here, we found that CX3CL1 was down-regulated in Wilms’ tumour." (PMID 35530333, 2022). "In contrast to low expression of the favorable prognostic marker CX3CL1 induced by epigenetic silencing, expression of CCL3, CCL8, CCL15, CCL18 and CXCL9 was negatively correlated with prognosis and T-cell infiltration in nephroblastoma." (PMID 37198402, 2023). "The expression of CX3CL1, CXCL14 and CXCL2 in nephroblastoma was significantly decreased." (PMID 35530333, 2022).
proliferative diabetic retinopathy (2 papers, 2015 to 2020). Advanced retinopathy due to diabetes mellitus characterized by the formation of new vessels in the retina. "CX3CL1 appeared to promote retinal angiogenesis in mice with oxygen-induced retinopathy (OIR), CX3CL1 levels are increased in the vitreous of patients with proliferative diabetic retinopathy and CD11b+ cells in the retina of diabetic mice have increased CX3R1 expression." (PMID 26710229, 2015). "Comparisons of vascular endothelial growth factor (VEGF), CXCL16, CX3CL1, ADAM10 and ADAM17 levels in proliferative diabetic retinopathy (PDR) patients with or without active neovascularization and nondiabetic patients with rhegmatogenous retinal detachment (RD)." (PMID 33552057, 2020).
relapsing remitting MS (2 papers, 2013 to 2018). "Studies are ongoing to investigate the correlation between serum levels of CX3CL1 in patients with relapsing remitting MS at different stages of their disease (relapse versus stable remission phase)." (PMID 24175290, 2013).
rheumatic diseases (2 papers, 2021 to 2024). "E6011, a monoclonal antibody that selectively binds to CX3CL1, has been developed for rheumatic diseases." (PMID 34063598, 2021).
sarcoma (2 papers, 2023 to 2024). A usually aggressive malignant neoplasm of the soft tissue or bone. "SQLE expression was negatively correlated with the expression of chemokines (CCL19 and CX3CL1) and chemokine receptors (CCR2 and CCR7) in sarcoma." (PMID 38335381, 2024). "In light of this, the TIMER2 database was utilized to investigate the possibility of a correlation between CX3CL1 and CD4+ T cell infiltration were observed in colon adenocarcinoma (COAD), LIHC, GBM, PRAD, KIRC, LUAD, HNSC, THCA, and sarcoma (SARC) based on the EPIC and TIMER algorithms." (PMID 37153002, 2023).
serous ovarian carcinoma (2 papers, 2015 to 2025). "We show that high CX3CL1 expression significantly correlates with worsened survival in human high-grade serous ovarian cancer (n=219)." (PMID 39862711, 2025). "In the present work, we have identified CX3CL1 for the first time as a prognostic marker for poor survival in patients with advanced high-grade serous ovarian cancer, independent of other classical risk factors." (PMID 39862711, 2025). "In opposite, both CX3CR1 and CX3CL1 are expressed in high-grade serous ovarian carcinoma." (PMID 26633537, 2015). "Both CX3CR1 and CX3CL1 are expressed by the serous ovarian carcinoma." (PMID 26633537, 2015).
Sjögren's syndrome (2 papers, 2020 to 2024). "A previous study showed that CTSS-mediated induction of CX3CL1 might contribute to the ocular surface and lacrimal glands inflammation in Sjögren's syndrome with a 4.5-fold increase in CX3CR1-expressing macrophages." (PMID 33553270, 2020).
thyroid cancer (2 papers, 2020 to 2023). "The results showed that CX3CL1 protein was less expressed in normal thyroid tissue but moderately expressed in thyroid cancer tissue." (PMID 33055358, 2020). "CX3CL1 expression was significantly elevated in cholangiocarcinoma (CHOL), kidney renal clear cell carcinoma (KIRC), kidney renal papillary cell carcinoma (KIRP), and thyroid carcinoma (THCA) tumor tissues compared to normal tissues." (PMID 37153002, 2023).
triple-negative breast carcinoma (2 papers, 2012 to 2022). An invasive breast carcinoma which is negative for expression of estrogen receptor (ER), progesterone receptor (PR), and human epidermal growth factor receptor 2 (HER2). "However, in another new clinical trial, the chemokine CX3CL1 was associated with shorter PFS in metastatic triple-negative breast cancer." (PMID 36397015, 2022). "Further studies validate CX3CL1 as a target of FGFR activity in the triple negative breast cancer cell line HS578T." (PMID 23029290, 2012). "Specifically, we illustrate that activation of both the inducible FGFR1 construct in mouse mammary epithelial cells and endogenous FGFR in the triple negative breast cancer cell line, HS578T, leads to expression of the chemokine CX3CL1." (PMID 23029290, 2012).
tuberculosis (2 papers, 2016 to 2017). A chronic, recurrent infection caused by the bacterium Mycobacterium tuberculosis. "In contrast, plasma CX3CL1 levels decreased after ESAT-6 stimulation (P < 0.05), suggesting that M. tuberculosis antigens other than ESAT-6 may be responsible for the elevated plasma CX3CL1 concentrations in TB patients." (PMID 26881918, 2016).
vitamin D deficiency (2 papers, 2022 to 2023). A nutritional condition produced by a deficiency of VITAMIN D in the diet, insufficient production of vitamin D in the skin, inadequate absorption of vitamin D from the diet, or abnormal conversion of vitamin D to its bioactive metabolites. "A decline in the CX3CL1 levels due to vitamin D deficiency may be related to decreased Aβ clearance." (PMID 36009371, 2022).
vitiligo (2 papers, 2022 to 2025). Generalized well circumscribed patches of leukoderma that are generally distributed over symmetric body locations and is due to autoimmune destruction of melanocytes. "In contrast to the findings in vitiligo, Th2 signaling was prominent as well, with consistent upregulation of CCL13, CCL17, CCL22, and CX3CL1." (PMID 40969764, 2025).
acute lung injury (1 paper, 2022). A condition of lung damage that is characterized by bilateral pulmonary infiltrates (pulmonary edema) rich in neutrophils, and in the absence of clinical heart failure. "In a lipopolysaccharide (LPS)-induced endotoxemic acute lung injury (ALI) rat model, berberine alleviated lung injury through different anti-inflammatory mechanisms; however, treatment effects on CX3CL1 expression and shedding remain to be examined." (PMID 35563195, 2022).
acute myelocytic leukemia (1 paper, 2021). "A study reported that CX3CL1 enhanced the phosphorylation of AKT in acute myelocytic leukemia cells." (PMID 34460437, 2021).
adult-onset Still disease (1 paper, 2020). A rare inflammatory multisystem disorder characterized clinically by fever of unknown origin, arthralgia or arthritis, hyperleucocytosis, and typical skin rash. "In addition, Kasama and colleagues reported that gene expression levels of Cx3cl1 and Il-18 are positively correlated with each other in adult-onset Still’s disease." (PMID 32941527, 2020).
alcoholic liver diseases (1 paper, 2018). A disorder caused by damage to the liver parenchyma due to alcohol consumption. "Therefore, the interplay between CX3CR1 and CX3CL1 might affect the progression of alcoholic liver disease." (PMID 30305672, 2018).
allergic disease (1 paper, 2024). An immune response that occurs following re-exposure to an innocuous antigen, and that requires the presence of existing antibodies against that antigen. "CX3CL1 and its receptor CX3CR1 were discovered more than twenty years ago, and a large amount of evidence has emerged linking the CX3CL1–CX3CR1 axis to various diseases, such as atherosclerosis, allergic diseases, neurodegeneration, and cancers." (PMID 38674036, 2024).
allergic rhinitis (1 paper, 2017). Inflammation of the nasal mucous membranes caused by an IgE-mediated response to external allergens. "Moreover, in allergic rhinitis, NK cells were shown to infiltrate the epithelial layers and the stroma of nasal tissue in response to CX3CL1 and CCL26." (PMID 28503177, 2017).
alopecia (1 paper, 2024). Hair loss usually from the scalp. "Photographic assessment demonstrated that control IgG-treated Scl-cGVHD mice showed mild and diffuse alopecia throughout the entire body surface on day 42 after BMT; however, the area and severity of alopecia were clearly reduced by both 0.5 mg and 1 mg doses of anti-CX3CL1 mAb treatment." (PMID 38702742, 2024). "Skin fibrosis and alopecia appeared on day 18 after BMT in both control IgG-treated and anti-CX3CL1 mAb-treated groups and gradually became apparent." (PMID 38702742, 2024).
aortic aneurysm (1 paper, 2025). A ruptured aneurysm located in the wall of the proximal portion of the descending aorta proceeding from the arch of the aorta. "Gene expression of CX3CL1 and CX3CR1 levels are elevated in lesions of aortic aneurysm and aortic dissection, and CX3CL1/CX3CR1 may be involved in these diseases as well, requiring further investigation." (PMID 40508161, 2025).
arteriosclerosis (1 paper, 2025). A vascular disorder characterized by thickening and hardening of the walls of the arteries. "Studies have demonstrated that inflammatory mediators such as fractalkine/CX3CL1, CCL8, M-CSF, HGF, E-selectin, PI3/elafin, CCL17, and IL-16 are significantly elevated in patients with AD, contributing to the progression of arteriosclerosis." (PMID 40757030, 2025).